FLNA (filamin A)
Description:
Promotes orthogonal branching of actin filaments and links actin filaments to membrane glycoproteins. Anchors various transmembrane proteins to the actin cytoskeleton and serves as a scaffold for a wide range of cytoplasmic signaling proteins. Interaction with FLNB may allow neuroblast migration from the ventricular zone into the cortical plate. Tethers cell surface-localized furin, modulates its rate of internalization and directs its intracellular trafficking (By similarity). Involved in ciliogenesis. Plays a role in cell-cell contacts and adherens junctions during the development of blood vessels, heart and brain organs. Plays a role in platelets morphology through interaction with SYK that regulates ITAM- and ITAM-like-containing receptor signaling, resulting in by platelet cytoskeleton organization maintenance (By similarity). During the axon guidance process, required for growth cone collapse induced by SEMA3A-mediated stimulation of neurons.
Synonyms: FLN-A; ABP-280; FLN; FLN1; ABPX; CSBS; CVD1; FGS2; FMD; MNS; NHBP; OPD; OPD1; OPD2; XLVD; XMVD
Tractability: Small molecule: a drug acting on it is in phase 2 or 3 trials; a structure with a bound ligand is known; it has a high-quality binding pocket. Antibody: its Gene Ontology location is reachable by antibodies, with high confidence. PROTAC: UniProt records ubiquitination sites on it; ubiquitination databases record sites on it; its protein half-life has been measured.
Target class: Structural protein
Gene: Protein-coding gene on chromosome X (154,348,524 to 154,374,638, reverse strand). Ensembl gene ENSG00000196924.
Subcellular location: Cytoplasm, cell cortex; Cytoplasm, cytoskeleton; Perikaryon; Cell projection, growth cone; Cell projection, podosome
Subcellular location (Human Protein Atlas): Actin filaments; Cytosol; Plasma membrane
Pathways (Reactome):
Hemostasis: GP1b-IX-V activation signalling; Platelet degranulation
Cell-Cell communication: Cell-extracellular matrix interactions
Immune System: OAS antiviral response
Signal Transduction: RHO GTPases activate PAKs
Gene Ontology:
Molecular function: actin filament binding; cadherin binding; DNA-binding transcription factor binding; Fc-gamma receptor I complex binding; G protein-coupled receptor binding; GTPase binding; kinase binding; potassium channel regulator activity; protein binding; protein homodimerization activity; protein sequestering activity; RNA binding; small GTPase binding; transmembrane transporter binding; protein-containing complex binding; SMAD binding
Biological process: actin crosslink formation; actin cytoskeleton organization; adenylate cyclase-inhibiting dopamine receptor signaling pathway; cilium assembly; establishment of protein localization; mitotic spindle assembly; negative regulation of apoptotic process; negative regulation of protein catabolic process; negative regulation of transcription by RNA polymerase I; platelet aggregation; positive regulation of canonical NF-kappaB signal transduction; positive regulation of integrin-mediated signaling pathway; positive regulation of potassium ion transmembrane transport; positive regulation of protein import into nucleus; positive regulation of substrate adhesion-dependent cell spreading; protein localization to cell surface; protein localization to plasma membrane; protein stabilization; receptor clustering; regulation of cell migration; semaphorin-plexin signaling pathway; tubulin deacetylation; wound healing, spreading of cells; blood coagulation, intrinsic pathway; megakaryocyte development; and 12 more
Cellular component: actin cytoskeleton; cell-cell junction; cytoplasm; cytosol; extracellular exosome; focal adhesion; membrane; Myb complex; nucleolus; nucleus; plasma membrane; extracellular region; glycoprotein Ib-IX-V complex; perikaryon; podosome; Z disc; actin filament; apical dendrite; cell cortex; cortical cytoskeleton; cytoskeleton; dendritic shaft; glutamatergic synapse; growth cone; neuronal cell body; and 2 more
Gene-disease validity (ClinGen):
ClinGen rates the evidence that FLNA causes each of these diseases.
periventricular nodular heterotopia (X-linked): Definitive. Periventricular nodular heterotopia (PNH) is a brain malformation, due to abnormal neuronal migration, in which a subset of neurons fails to migrate into the developing cerebral cortex and remains as nodules that line the ventricular surface.
familial thoracic aortic aneurysm and aortic dissection (X-linked): Limited. A rare genetic vascular disease characterized by the familial occurrence of thoracic aortic aneurysm, dissection or dilatation affecting one or more aortic segments (aortic root, ascending aorta, arch or descending aorta) in the absence of any other associated disease.
Homologues: Orthologues: macaque FLNA (99% identical), dog FLNA (98% identical), guinea pig FLNA (98% identical), rat Flna (97% identical), mouse Flna (97% identical), chimpanzee FLNA (97% identical), pig FLNA (96% identical), tropical clawed frog flna (86% identical), rabbit RA_M006_JSM7BED4F (29% identical). Paralogues in human: FLNC (73% identical), FLNB (69% identical), MACF1 (15% identical), DST (14% identical), PLEC (14% identical), SPTBN1 (12% identical), SPTB (12% identical), SYNE1 (12% identical), SYNE2 (11% identical), SPTBN4 (11% identical), SPTBN2 (11% identical), SPTBN5 (11% identical), and 24 more.
Diseases named in the same sentence as FLNA in open-access papers:
FLNA is named in the same sentence as 274 diseases in open-access papers, as found by Europe PMC text mining. Sharing a sentence is not in itself a finding about the gene and the disease. The quoted sentences say what the papers report.
melanoma (52 papers, 2009 to 2025). A malignant, usually aggressive tumor composed of atypical, neoplastic melanocytes. "Our results are similar to previous findings that FLNA deficiency impaired cell motility by affecting the arrangement of F-actin in human seminoma cells and melanoma cells." (PMID 39399465, 2024). "These FLNA-deficient human melanoma cells exhibited different actin organization and were unable to maintain surface stabilization and support movement." (PMID 39399465, 2024). "High levels of FLNA were associated with longer OS in colorectal cancer, while in gastric cancer and melanoma FLNA expression is associated with poor OS, corroborating the idea that the effects of FLNA are cancer-type specific." (PMID 38068896, 2023). "In melanoma, PrPC also exists in the pro-PrPC form, and in FLNa deficient melanoma cell lines, modulations in the PRNP gene expression affect cell migration." (PMID 32932634, 2020). "We selected B16F10 mouse melanoma cells, metastatic A375M human melanoma cells, filamin-A-deficient M2 human melanoma cells, and THP-1 human acute monocytic leukemia cells." (PMID 30526524, 2018). "In keratinocytes Filamin A (FLNA), a cytoskeletal SMAD-binding protein, binds SMAD2 for effective TFGβ receptor signaling; accordingly, FLNA-deficient melanoma cells have impaired TGFβ signaling." (PMID 26700622, 2016). "This notion was further supported by the observations that overexpression of filamin A is associated with highly metastatic cancers, such as melanoma, neuroblastoma, breast cancer, and prostate cancer." (PMID 25944616, 2015). "We next used human melanoma M2 cells deficient of filamins and FLNA-replete A7 cells for similar experiments." (PMID 25861040, 2015). "Here we studied the effects of filamin on PC2 stability using filamin-deficient human melanoma M2, filamin-A (FLNA)-replete A7, HEK293 and IMCD cells together with FLNA siRNA/shRNA knockdown (KD)." (PMID 25861040, 2015). "For example, in lung cancer, FLNa overexpression was shown to be associated with tumor metastasis, and in melanoma, FLNa-positive cells had higher migration and invasion abilities compared with FLNa-negative tumor cells." (PMID 24137390, 2013). "Previous studies with FLNa-deficient melanoma cells show that FLNa is required for cell polarization and migration toward a chemoattractant." (PMID 24205360, 2013). "We demonstrate an association between R-Ras and FLNa and that the resulting complex can significantly enhance melanoma migration and increase integrin activation and fibronectin matrix assembly." (PMID 20585650, 2010). "A role for FLNs in cell migration was first proposed 17 years ago based on the phenotype of FLNa-deficient melanoma cells." (PMID 19915675, 2009). "FLNa-deficient M2 melanoma cells exhibit a characteristic plasma membrane blebbing but we did not observe blebbing in FLNaKD cells, either during routine cell culture or 1 hour after plating on FN." (PMID 19915675, 2009). "Filamin-A null melanoma cells are more susceptible to radiation than Filamin-A proficient cells." (PMID 40282554, 2025). "In addition to chemotherapeutic drugs, filamin-A deficiency sensitizes melanoma and breast cancer cells to ionizing radiation." (PMID 23388158, 2013). "Blocking calpain‐induced cleavage of filamin A has been shown to decrease proliferation, migration, and colony formation in several types of cell lines, such as human melanoma, human prostate cancer, mouse fibrosarcoma, and mouse pancreatic cells." (PMID 40151834, 2025). "Filamin-A re-expression in the Filamin-A null melanoma cells increased HR RAD51 foci formation and cell survival after γ-radiation." (PMID 40282554, 2025). "Calpain‐mediated filamin A cleavage has been reported to control HIF1α activity in several cancer cell lines, including melanoma, osteosarcoma, and cervical cancer cells." (PMID 40151834, 2025).
melanoma (continued). "Filamin A has since shown to be phosphorylated in a variety of different cells including fibroblasts, smooth muscle, endothelial cells and human melanoma lines." (PMID 38958472, 2024). "have shown that hypoxia promotes calpain-induced filamin-A proteolysis in melanoma cells, which in turn facilitates HIF-1α nuclear translocation." (PMID 39156707, 2024). "Since then, these melanoma cell lines have been used to study the function of FLNA, both in vitro and in vivo, and identify interaction partners in health and disease." (PMID 39195282, 2024). "In melanoma cells, extracellular S1P activated NFκB, and this was correlated with expression of actin-binding protein FlnA, an interaction partner of SPHK1 and TRAF2." (PMID 36672428, 2023). "To further investigate the involved mechanism, we took advantage of M2 cells, a widely used melanoma cell model that lacks endogenous FLNA expression, and A7 cells, a control M2 clone in which FLNA was reintroduced by stable transfection." (PMID 36596803, 2023). "We next validated the relationship between TRIP13 and FLNA expression in tissue specimens of melanoma patients." (PMID 36268276, 2022). "Wnt5a leads to the remodeling of the cytoskeleton and increases melanoma motility by activating calpain-1, leading to the cleavage of filamin A." (PMID 35162934, 2022). "Together, we propose a model in which TRIP13 activates the PI3K/AKT signaling to transcriptional activation of N-cadherin and inhibition of E-cadherin through the interaction with FLNA and then induces melanoma cell migration, invasion, and EMT." (PMID 36268276, 2022). "In agreement with our previous studies demonstrating a complex consisting of MRTF-A and FLNA, we additionally found an interaction between MRTF-A and LPAR1 in HuH7 HCC cells and M2 melanoma cells expressing FLNA." (PMID 36577757, 2022). "TRIP13 overexpression was associated with a malignant phenotype of melanoma, and the interaction of TRIP13 and FLNA activated the PI3K/AKT pathway to induce EMT in melanoma cells." (PMID 36268276, 2022). "In melanoma cell models, the expression of FLNA allows the plasma membrane localization of D2DR, whereas, in absence of FLNA, D2DR is predominantly localized in the cytoplasm compartment." (PMID 35095761, 2021). "Several studies revealed that FLNA expression supports oncogenic diseases in humans such as melanoma, lung and hepatocellular cancer, whereas FLNA protein was decreased in breast cancer." (PMID 33266100, 2020). "As a potential interactor of Pro-PrP, the actin-binding protein FLNA has been identified in melanoma cells." (PMID 31752162, 2019). "S1P1 has also been shown to co-localise with SK1 and filamin A in lamellipodia in filamin A-expressing A7 melanoma cells, and this is required for cell motility and is blocked by an S1P1 antagonist." (PMID 28241498, 2017). "Coincident with this, two recent reports showed that Wnt5A and hypoxia also activate the calpain-mediated cleavage of filamin A and increases melanoma cell motility." (PMID 27206800, 2017). "Some studies later showed that filamin A can be cleaved into two fragments (~100 kD and 180 kD) in prostate cancer cells, HeLa cells and A7 melanoma cells." (PMID 27206800, 2017). "Of great interest, the process involved a gradual accumulation of Filamin A (FlnA), an actin-binding protein that we recently demonstrated to modulate S1P-induced NF-κB activation in melanoma cells." (PMID 27800303, 2016). "From previous studies, FLNA appears to be overexpressed in several types of cancers, such as prostate cancer, breast cancer, lung cancer, colon cancer, melanoma, and neuroblastoma." (PMID 26134617, 2015). "FlnA/PTPN12 interactions were then challenged in a pulldown assay using the interaction domain of PTPN12 fused to GST protein and melanoma cell lines stably expressing FlnA-WT and FlnA-P637Q." (PMID 26594644, 2015).
melanoma (continued). "FLNa was reported to be essential for the locomotion of human melanoma cells, and the suppression of FLNa expression inhibited melanoma cell migration and induced apoptosis." (PMID 24137390, 2013). "Recently, we have shown that knockdown of filamin-A in melanoma C8161 cells reduced metastasis in xenograft mouse models, and that filamin-A inhibition reduced the mobility and invasiveness of breast cancer cell lines that do not over-express ErbB2 in vitro." (PMID 23388158, 2013). "The FLNa protein also interacted with the GTP-binding protein R-Ras to promote metastasis of melanoma cells." (PMID 24137390, 2013). "Wnt5A activates calpain-1, leading to the cleavage of filamin A, which results in a remodeling of the cytoskeleton and an increase in melanoma cell motility." (PMID 23388158, 2013). "M2 melanoma cells have diminished expression of Filamin A, an F-actin cross-linking protein, and constitutively extrude large blebs with extended half-lives." (PMID 23024796, 2012). "Our findings indicate that the FLNa-EGFP construct was correctly expressed, cleaved by calpain and colocalized with actin filaments as shown by immunostaining experiments in the human melanoma cell lines A7 (FLNa-repleted) and M2 (FLNa-deficient)." (PMID 22870205, 2012). "RRAS binds FLNA (filamin A) (interaction 2), and this combination was required for migration of melanoma cells (see section below on FLNA)." (PMID 22570691, 2012). "In this connection, RSK was shown to enhance the migration of melanoma cells through phosphorylation of the cytoskeletal protein filamin-A." (PMID 22216126, 2011). "We further show that the complex is functional in that R-Ras and FLNa expressing melanoma cells demonstrate significant increased migration." (PMID 20585650, 2010). "R-Ras was detected in FLNa immunoprecipitations confirming that R-Ras and FLNa are in a complex in mammalian melanoma M2 cells." (PMID 20585650, 2010). "A previous study showed that filamin-A interacts with BRCA2, and lack of filamin-A expression results in increased cellular sensitivity to several DNA-damaging agents in melanoma cells." (PMID 19367286, 2009). "Moreover, Filamin-A knockdown in other melanoma and breast cancer cells decreased their survivability post-DNA damage induction." (PMID 40282554, 2025). "Filamin A cleavage plays a pivotal role in melanoma cells, particularly during metastasis." (PMID 38958472, 2024). "Additionally, to detect the role of FLNA in TRIP13-induced melanoma progression, we performed a series of rescue assays." (PMID 36268276, 2022). "co-IP assays further confirmed the physical interaction of TRIP13 and FLNA in melanoma cells." (PMID 36268276, 2022). "While there are findings showing a significant decrease in filamin A levels in tissues from invasive breast cancer (BC) compared with benign disease on the one hand, tumorigenic enhancing activity in melanoma, lung and hepatocellular cancers has also been reported on the other." (PMID 34771736, 2021). "The discovery of multiple FLNA-deficient melanoma cells has prompted scientists to study the cellular functions in the presence or absence of FLNA and interacting partners of FLNA in further detail." (PMID 34207234, 2021). "In fact, FLNA is overexpressed in multiple types of tumors, including prostate, breast, lung cancer, hemangiomas, colon cancer, melanoma, neuroblastoma, squamous cell carcinoma, hepatic cholangiocarcinoma, suggesting a possible correlation with FLNA and cancer aggressiveness." (PMID 29100390, 2017). "Filamin-A (FLNa) has been shown to be a key cross-linker of actin filaments in the leading edge of a motile melanoma cell line, however its role in neutrophils undergoing chemotaxis is unknown." (PMID 24205360, 2013).